MSLN (mesothelin)
Diseases named in the same sentence as MSLN in open-access papers (continued):
Sharing a sentence is not in itself a finding about the gene and the disease.
tumor (continued). "In conclusion, we developed a new Nb targeting MSLN, regardless of the presence of its ligand MUC16, and used it successfully to detect MSLN-positive tumours in vivo." (PMID 37388728, 2023). "The expression of MPM markers was analyzed using IHC and positive tumor cells were quantified: all tumors were positive for Calretinin, Mesothelin, and Podoplanin, with an average of positive tumor cells/sample of 79%, 87%, and 61%, respectively." (PMID 37345150, 2023). "In recent decades, a significant number of studies examined MSLN as a therapeutic target based on its differential expression profile between healthy tissue and tumours, and its prognostic impact." (PMID 37388728, 2023). "Equally significant was the higher expression of MSLN in 46.8% of epithelioid tumor cells compared with 0.0% in the sarcomatoid histotype (P = 0.003)." (PMID 37901248, 2023). "A similar expression of MSLN by tumor cells was observed according to tumor infiltrating lymphocyte (TIL) scores (P = 0.70)." (PMID 37901248, 2023). "Current studies have shown that mesothelin can play a role in the process of tumor cell proliferation, tumor invasion and metastasis, and tumor drug resistance." (PMID 36705352, 2023). "In a mouse model of non-small cell lung cancer, anti-MSLN CCR2b CAR-T cells had better tumor tissue infiltration and antitumor function." (PMID 36900151, 2023). "Studies have shown that MSLN can promote tumor proliferation, metastasis, and resistance to chemotherapy." (PMID 37359558, 2023). "Only one trial of a genetically modified T cell receptor fusion construct required 2+/3+ MSLN expression in ≥ 50% viable tumour cells by IHC as its sole inclusion criterion relating to MSLN expression." (PMID 37040900, 2023). "YAP and MSLN are co-expressed in fibrolamellar carcinoma, and have been suggested to be potential therapeutic targets for the treatment of this tumor type." (PMID 37835395, 2023). "Sixty‐six per cent of epithelioid tumours were MSLN‐positive (with expression in > 5% tumour cells)." (PMID 37040900, 2023). "When tested in xenograft models in vivo, CAR-NK cell therapies using primary human NK cells targeting CD19, HER2, and mesothelin yielded increased responses to tumor cells in vitro and suppressed tumor growth." (PMID 36768432, 2023). "48.6% of all samples showed an overall strong staining (Score ≥ 2), 59% of the investigated tumours showed MSLN protein expression (10.5% of them at high expression (Score 3)), and 36.2% of all samples showed an overall strong staining (Score ≥ 2)." (PMID 37047331, 2023). "Cox multivariate analysis showed a high risk of death for non-operated patients [hazard ratio (HR), 3.42 (1.15–10.16)] with low tumor mesothelin levels [HR, 2.58 (1.09–6.10)] and high PD-L1 and low infiltration of T cells CD4+ [HR, 3.81 (1.58–9.18)]." (PMID 37901248, 2023). "Of MSLN‐expressing epithelioid tumours, 70.4% had moderate (2+) or strong (3+) intensity MSLN immunostaining, although only 37% of samples had staining in ≥ 50% of tumour cells." (PMID 37040900, 2023). "The relationship between MSLN expression by tumor cells and the density of elastic and collagen fibers in the TME was examined next." (PMID 37901248, 2023). "Another promising approach is the use of anti-MSLN Chimeric Antigen Receptor (CAR) T-cell therapy directed toward tumor antigens, such as mesothelin." (PMID 37445594, 2023). "The tracer tumor uptake (SUVmax on day 4) correlated with MSLN expression, as determined by immunohistochemistry (IHC) on archival tumor tissue." (PMID 35326605, 2022). "This molecule was designed to engage the TME due to the overexpression of mesothelin by several types of tumor cells." (PMID 35911742, 2022). "These anti-PD-1 CAR-T cells had lower PD-1 expression, higher levels of T cell activation, and better anti-tumor activity, specifically against MSLN- and PD-L1-positive tumor cells both in vitro and in vivo." (PMID 35326556, 2022).
tumor (continued). "In this study, we designed a novel fusion peptide immunogen including human MSLN, PD-L1 immune checkpoint molecule, GM-CSF sequence and T helper epitope sequence assembly as therapeutic tumor vaccine (MSLN-PDL1-GMCSF)." (PMID 35795680, 2022). "Recently, BsAbs targeting the MSLN and CD3 proximal area epitopes have increased lifetimes by increasing T cell activation and decreasing the tumor’s bone marrow AML cell load in MSLN-positive mice." (PMID 36389699, 2022). "In this study, only PRDM1/NR4A3 double knockout anti-mesothelin CAR T-cells mediated a significant reduction in tumor burden over time (P < 0.05, fig." (PMID 36350986, 2022). "The integration of CAR-NK-92 cells targeting mesothelin and cGAMP presented better anti-tumor effects compared with individual treatment in a mouse model of pancreatic cancer by improving tumor control and promoting survival." (PMID 35889509, 2022). "MSLN is a cell adhesion glycoprotein and its overexpression was positively correlated with high tumor aggressiveness and poor prognosis in patients with thoracic malignancies." (PMID 35911706, 2022). "Consistently, CARs with two costimulatory domains (CD28-4-BB) targeting PSMA and mesothelin showed superior tumor eradication and increased persistence in solid tumor models compared with single domain-based CARs45,46." (PMID 35729339, 2022). "The results showed that mesothelin-CAR-NK cells exhibited similar anti-tumor activity to CAR-T cells in vivo, and the toxicity was lower." (PMID 36032149, 2022). "Our results showed that the novel PD-L1-containing MSLN targeting vaccine was able to activate a MSLN and PD-L1-specific T cell immune responses in immunized mice, inhibit the growth of MSLN+ and PD-L1+ tumor cells." (PMID 35795680, 2022). "MSLN was expressed at high levels (76–100%) in 11/14 cases, and in 3/14 cases, 100% of tumor cells presented MSLN positivity." (PMID 35162954, 2022). "Preclinical studies of mesothelin targeting CAR-T cells have shown significant tumor reduction and are currently under clinical evaluation by many groups." (PMID 35326701, 2022). "Researchers have found that the abnormal expression of MSLN plays an important role in tumor cell growth, invasion and metastasis." (PMID 35692779, 2022). "Mesothelin (MSLN) is a tumor differentiation antigen normally expressed on the mesothelial cells lining the pleura, peritoneum, and pericardium." (PMID 36158673, 2022). "MSLN can promote tumor invasion and malignant transformation, and it is highly expressed in epithelioid and biphasic PM, but not in sarcomatoid histotype." (PMID 35328227, 2022). "Mesothelin (MSLN)-CAR-T cells can effectively inhibit the growth of GC cells in the Patient-derived tumor xenograft (PDX) model." (PMID 36341377, 2022). "In this study, we first checked the MSLN expression in 33 tumor types using the TCGA Universal Cancer Database." (PMID 35692779, 2022). "Mesothelin is a highly desirable target for tumor-specific immunotherapy given its overexpression in tumor cells and relative paucity in normal healthy cells." (PMID 35326701, 2022). "MSLN expression was also significantly correlated with CD11c+ in the metastatic sites and in the perivascular areas of the primary neoplasm." (PMID 35565412, 2022). "CAR-T cells with CEA and MSLN as dual targets can accurately locate the tumor site and have higher toxicity to pancreatic malignancy." (PMID 36428765, 2022). "The authors observed that neoplasms with a high expression level of mesothelin showed a statistically worse prognosis than those with low immunoreactivity." (PMID 35565412, 2022). "Altogether, these results suggest that NFAT signaling-regulated CCL19 can be induced by tumor cell-surface mesothelin in vitro." (PMID 35990619, 2022). "CA125 and mesothelin interactions are thought to provide the first step in tumor cell invasion of the peritoneum." (PMID 35285179, 2022).
tumor (continued). "A meta-analysis summarized the relationship between potential biomarkers and malignancy of THYM and suggested that mesothelin (MSLN) has a significant relationship with tumor proliferation and degree of malignancy." (PMID 35222524, 2022). "Bioengineered Listeria monocytogenes designed to express mesothelin, a PC-associated tumor antigen, induced the efficient activation of cytotoxic CD8+T cell responses, inducing PC tumor regression." (PMID 35741028, 2022). "A fusion protein targeting MSLN was found to promote tumor-specific T cell responses by increasing tumor antigen presentation and cross-presentation via DC in vitro and enhanced tumor cell immunogenicity in vivo." (PMID 35795680, 2022). "MSLN has also been regarded as an attractive target for chimeric antigen receptor T cell (CAR T) therapy because of its abundant expression in tumour cells and its limited expression in normal cells." (PMID 35565412, 2022). "MSLN expressed at low levels in normal tissues acts as a tumor differentiation antigen.MSLN is a glycosylphosphatidylinositol-anchored protein that was first described as a membrane protein expressed in normal and neoplastic mesothelial cells." (PMID 36458008, 2022). "For example, Lm vaccines against the tumor-associated antigens PAP and mesothelin had poor immunogenicity alone but were more effective as booster vaccines in the context of a heterologous prime-boost immunization regimen, similar to observations with GUCY2C." (PMID 35355987, 2022). "Here, we demonstrate that patients with a high presentation of MSLN in their tumor immunopeptidome, in terms of unique MSLN-derived HLA class II-presented peptides, exhibited a prolonged PFS and OS." (PMID 35565389, 2022). "Two different signaling domains (CD3ζ and CD28) were constructed in two separate CARs and in one T cell to target two different antigens (mesothelin and FRα) in one tumor cell." (PMID 35414783, 2022). "It is worth noting that recombinant antibodies against mesothelin, which has a cleaved soluble isoform that accumulates in the tumor matrix, have already been tested in the clinical setting." (PMID 36303838, 2022). "MSLN can also promote peritoneal colonization and metastasis of tumor cells by promoting tumor angiogenesis." (PMID 35692779, 2022). "In a previous publication, we identified OvCa-associated HLA class I- and HLA class II-presented tumor antigens with MUC16 and MSLN representing the two main tumor antigens for HLA class I and HLA class II, respectively." (PMID 35565389, 2022). "Conversely, neoplasms with focal MSLN expression can progress given that neoplastic cells cannot be detected by the immune system and will continue to develop." (PMID 35565412, 2022). "In the tumor environment, MSLN plays an important role in survival, proliferation, and migration/invasion of cancer cells as well as in drug resistance." (PMID 35795680, 2022). "Preconditioning with the TAM-targeted CAR T cells enhanced the efficacy of tumour-specific anti-mesothelin CAR T cells, with tumour regression and extended survival." (PMID 35205725, 2022). "The preclinical data using this antibody-based therapy were promising as combination of treatment of SS1P with radiation, taxol or gemcitabine resulted in enhanced antitumor activity against mesothelin-expressing tumour xenografts." (PMID 35892707, 2022). "In xenograft models, the A2aR-disrupted anti-mesothelin CAR-T cells decreased the tumor burden compared to unmodified T cells and anti-mesothelin CAR-T cells." (PMID 35326701, 2022). "Given its limited expression in normal tissues and overexpression in several tumor cells, mesothelin presents a desirable target for tumor-specific therapy." (PMID 35326701, 2022). "Available data identify a potential role of mesothelin in tumor cell adhesion, progression, proliferation, survival, and resistance to chemotherapy, although the definitive mechanisms have yet to be fully elucidated." (PMID 35326701, 2022).
tumor (continued). "Mesothelin (Msl) mice expressed human mesothelin typically in the serosal membrane and were used to assess on-target, off-tumor toxicity of human mesothelin-targeted therapeutics." (PMID 36136517, 2022). "The CRS-207 vaccine uses attenuated Listeria monocytogenes (Lm) (Lm ΔactA/ΔinlB) bacteria that are engineered to express human MSLN and can be used to treat MSLN-positive neoplasms." (PMID 35565412, 2022). "We also briefly examine the latest progress in mesothelin-targeting therapies for this aggressive and lethal neoplasm." (PMID 35565412, 2022). "The biological explanation for this is based on the roles played by S100A4, Ca-125, and mesothelin in promoting tumor invasion and metastasis." (PMID 35892879, 2022). "Aberrant MSLN expression plays an important role in tumor cell proliferation and invasion by inducing the activation of matrix metalloproteinase (MMP)." (PMID 36059490, 2022). "Mesothelin (MSLN) is a glycoprotein located in the mesothelial lining of the body’s cavities and in many neoplasms." (PMID 35565412, 2022). "Phase I studies have shown that mesothelin targeting CAR-T cells are well tolerated with minimal on-target off-tumor effects but showed limited clinical activity." (PMID 35326701, 2022). "That 66 of our 122 analyzed tumor entities contained MSLN positive cases demonstrates that a positive MSLN expression cannot be viewed as an argument for a specific tumor entity." (PMID 33917081, 2021). "Due to the characteristic of MSLN, it has become the focus of specific targeting antigen of tumor cells." (PMID 35111680, 2021). "We successfully expressed a panel of novel CAR architectures in NK-92 cells using PB or SB systems and demonstrated improved anti-tumor activities of CAR-expressing NK-92 cells when co-cultured with mesothelin-expressing targets." (PMID 34134774, 2021). "Herein, using bioinformatics and clinical samples, we identified two candidate proteins, folate receptor 1 (FOLR1) and mesothelin (MSLN), that were highly expressed in tumor tissues but exhibited low expression in normal tissues." (PMID 34803504, 2021). "The other tumor antigen is taken from mesothelin (MSLN), a glycosylphosphatidylinositol-anchored cell surface protein that is expressed at low levels on normal mesothelial cells." (PMID 34838059, 2021). "A non-tumor cell line expressing a chimeric MSLN/Nectin-1 receptor, de-sensitized from antiviral responses by genetic inactivation of the Stimulator of Interferon Genes (STING)-dependent pathway was engineered, to optimize viral yields." (PMID 33418877, 2021). "In a patient with advanced PC, anti-MSLN-7 × 19 CAR-T treatment resulted in almost complete tumor disappearance 240 days post-intravenous infusion." (PMID 34325726, 2021). "To further explore how host MSLN expression impacts tumor burden, we analyzed omental metastases for tumor-infiltrating lymphocytes (TILs) and macrophages using a pan-b cell marker (CD45R) and pan macrophage (F4/80) marker." (PMID 34830322, 2021). "Blocking PKA localization to the immune synapse led to increased anti-MSLN CAR T cell migration to the tumor as well as enhanced anti-tumor efficacy in a MM mouse model." (PMID 33588928, 2021). "MUC16 and mesothelin interactions are thought to provide the first step in tumor cell invasion of the peritoneum." (PMID 34150633, 2021). "In Taxol-sensitive tumors, mesothelin shedding into the tumor environment and in blood was significantly reduced (~10 times) over 5 days after a single injection of 20 mg/kg of Taxol." (PMID 34976821, 2021). "At least an occasional weak MSLN positivity was detected in 66 of 122 (54.1%) different tumor types and tumor subtypes and 50 (41.0%) tumor types and subtypes had at least one tumor sample exhibiting strong positivity." (PMID 33917081, 2021). "MSLN is expressed in only few normal tissues but has been found to be overexpressed in various tumor types at a relevant frequency." (PMID 33917081, 2021).
tumor (continued). "The preclinical studies revealed that amatuximab induced antibody-dependent cellular cytotoxicity of mesothelin-expressing tumor cells in in vitro studies and significantly reduced mesothelin-positive tumors in the xenograft model." (PMID 34361048, 2021). "Another preclinical study validated the use of CAR-engineered NK cells targeting mesothelin and demonstrated robust anti-tumour NK cell-dependent activity in OC mouse models." (PMID 34944851, 2021). "Due to the role of the MSLN–MUC16 interaction in tumor progression, the MSLN MDR has become the main target for existing immunotherapy strategies." (PMID 34439085, 2021). "Recent studies have demonstrated a role for mesothelin in cell survival, cell migration, cell invasion and tumor progression." (PMID 33637083, 2021). "Tumor burden seems to correlate with MPF levels, and reduced MPF levels in the sera of patients receiving anti-MSLN immunotoxin SS1P therapy are associated with improved progression-free and overall survival rates." (PMID 34439085, 2021). "A total of 68 (14%) patients had a tumor proportion score of 3+, while 166 had a staining intensity score of 2+ on mesothelin staining Among the 485 patients, 171 (35%) were positive for mesothelin expression." (PMID 33832498, 2021). "Specifically, there is a 48% to 76% probability of near-completely eliminating tumor by targeting FOLR1 or MSLN alone, while targeting FOLR1 and MSLN simultaneously was predicted to kill more than 88% of cancer cells based on a cohort of 160 OVs." (PMID 34803504, 2021). "Prior work has identified some of the molecular components that a tumor cell can utilize to attach to this barrier, including vitronectin, hyaluronic acid, mesothelin, fibronectin, and P-selectin." (PMID 34396026, 2021). "High rates of MSLN expression have already been described for these tumor entities, although the results varied between studies." (PMID 33917081, 2021). "Mesothelin (MSLN), a tumor-associated antigen, is broadly overexpressed on various malignant tumor cells, making it as an attractive candidate for targeted therapy." (PMID 33828176, 2021). "Mesothelin, a tumour differentiation antigen found in mesothelial pleura, peritoneum and pericardium, was discovered in 1996 at the National Cancer Institute." (PMID 33800113, 2021). "MSLN, a glycoprotein on the cell surface, is overexpressed in many cancers and is relevant to novel anti-cancer treatment by regulating the tumor microenvironment." (PMID 33995018, 2021). "As CRS-207 targets mesothelin, a tumor antigen highly expressed in MPM, a Phase I clinical trial was conducted to determine safety and tolerability of CRS-207 in combination with pemetrexed and cisplatin." (PMID 33936058, 2021). "The first one tested anti-mesothelin CAR transduced peripheral blood lymphocytes in various tumor types expressing mesothelin, including CC." (PMID 33671294, 2021). "PDAC expresses TAAs such as mesothelin but is poorly infiltrated by T cells and is considered an immunologically “cold” tumor." (PMID 33936058, 2021). "Typical features include an ectodomain, containing the single-chain variable fragment (scFv) that identifies and binds to a specific tumor antigen (in this case, MSLN), a hinge, a transmembrane domain, and an endodomain that contains the signaling domains." (PMID 34439085, 2021). "Another phase I trial on OC is currently evaluating the safety and efficacy of CAR-T cells based on ten different tumor-specific antibodies in several tumor types; anti-mesothelin and anti-C-met CAR-T cells are among the treatments administered to patients." (PMID 33671294, 2021). "Mesothelin is involved in a variety of tumor-promoting pathways such as STAT3, NFκB, ERK, and PI3K/Akt." (PMID 34522225, 2021). "It is expressed at low levels in healthy mesothelial cells of the pleura, pericardium and peritoneum, whereas virtually every MM case exhibits significant MSLN expression in the tumor biopsy." (PMID 33588928, 2021).